MTOR (mechanistic target of rapamycin kinase)
Diseases named in the same sentence as MTOR in open-access papers (continued):
Sharing a sentence is not in itself a finding about the gene and the disease.
melanoma (continued). "In Melanoma cases, it has been reported that apigenin activates the cleaved caspase-3, PARP expression sites, downregulate Twist1, MMP-2/9, VEGF, p-mTOR, ERK1/2 proteins and p-AKT, deactivate FAK/ERK1/2 pathways and silenced STAT3 phosphorylation." (PMID 33794890, 2021). "It was also shown that resveratrol suppressed the growth of B16F10 murine melanoma cells and A375 human cells by promoting autophagy and inhibiting the PI3K/AKT/mTOR signaling pathway." (PMID 34575899, 2021). "Our results provide evidence that mTOR inhibitor in combination with BRAF and MEK inhibitors blocked the growth of CR melanoma cells primarily due to cell cycle arrest." (PMID 34304249, 2021). "At the same time, a recent report revealed that FADS2-mediated sapienate metabolism is regulated by the mTOR-SREBP1/2 axis, providing another possibility for the regulatory mechanism of FADS2 in melanoma." (PMID 37849907, 2021). "In melanoma and HCC, intrinsic PD-1 activity sustains tumour growth through an mTOR/S6K1 signalling." (PMID 33413561, 2021). "Human and dogs with melanoma have shown alterations in similar signaling pathways including RAS/MAPK, PI3K/Akt, and mTOR." (PMID 33544704, 2021). "RSV also suppressed the growth of A375 human melanoma cells and B16 F10 murine melanoma cells by promoting autophagy and inhibiting the PI3K/AKT/mTOR signaling pathway." (PMID 33467015, 2021). "In melanoma, high levels of BRAF‐V600E concomitantly trigger a senescent‐like phenotype and autophagy through mTOR downregulation; inhibiting autophagy allowed cells to resume proliferation." (PMID 34355491, 2021). "Contrastingly, Panduratin A was shown to induce protective autophagy in melanoma A375 cells by activating AMPK and inhibiting mTOR signal transduction, thereby, conferring an antiapoptotic effect." (PMID 33231372, 2021). "c-MET/EGFR/PI3K/mTOR are therapeutic targets for NSC777205 and NSC777207 with consequent selective cytotoxic preferences for melanoma, renal, CNS, colon, and NSCLC cell lines." (PMID 34512327, 2021). "Kaempferol exerts strong anticancer effects through inducing apoptosis, cell migration, cell cycle arrest at the G2/M phase, inhibiting and reducing the level of mTOR, pm-TOR, PI3K, p-PI3K, and Akt protein levels in the human malignant melanoma A375 cell line." (PMID 34830339, 2021). "Curcumin is able to prevent invasion by inhibiting AKT, mTOR and P70S6K phosphorylation, as demonstrated in human melanoma A375 and C8161 cells and TC1889 human thymic carcinoma cells." (PMID 34680593, 2021). "The most important pathways are glycolysis, TCA cycle, glutamine pathway, PPP pathway, HBP connected with the glycan biosynthesis pathway and in case of melanoma MAPK and mTOR pathways." (PMID 33730175, 2021). "Collectively, our study revealed that structural hybridization strategies yielded novel and potential c-MET/EGFR/PI3K/mTOR multi-target compounds, NSC777205 and NSC777205, with promising prospects for treating melanoma, renal, CNS, colon, and NSCLC cell lines." (PMID 34512327, 2021). "TM’s anti-melanoma apoptosis-inducing effects were uncoupled from serotonin signaling and attributed to PI3K/Akt/mTOR signaling inhibition." (PMID 32085796, 2020). "Recently, miR-26b-5p has been shown to target the MAPK and AKT/mTOR signaling pathways by binding to the 3′ UTR of TRAF5 or TRIM44, respectively, which are involved in the malignant progression of melanoma cells." (PMID 32825219, 2020). "Based on this idea, the effect of FKB on the expression of AKT (Ser437) and mTOR (Ser2448) was demonstrated and we found that 10 μg/mL FKB treatment significantly downregulated mTOR expression, inferring increased autophagy in FKB activated melanoma cells." (PMID 33053749, 2020). "Common driver oncogenic pathways critical to melanoma pathogenesis are the MAPK and PI3K/Akt and mTOR pathways." (PMID 32085796, 2020).
melanoma (continued). "TMZ has been combined with inhibitors that target not only MGMT, NF-κB, and Notch signaling but also AKT, mTOR signaling, autophagy, and glutaminase-mediated glutamine metabolism, all of which significantly enhanced TMZ cytotoxicity in melanoma cells." (PMID 32899791, 2020). "In clinical phase I trial, the combination of mTOR inhibitor temsirolimus and autophagy inhibitor hydroxychloroquine (HCQ), augmented cell death in patients with advanced solid tumors and melanoma." (PMID 33239065, 2020). "In BRAF inhibitor-resistant melanoma cells, a combination of MEK inhibitors with phosphatidylinositol 3-kinase (PI3K) or mechanistic target of rapamycin (mTOR) inhibitors can significantly decrease cancer cell survival." (PMID 32531927, 2020). "In conclusion, our study is the first demonstration of an antitumor activity of OA by controlling the altered pattern of gene expression (transcripts and miRNAs) related to mTOR and BCL2 pathways in melanoma cells." (PMID 33071785, 2020). "All our tested melanoma cell lines both BRAFV600E and BRAF WT were sensitive to AKT, PI3K and pan-mTOR inhibition with IC50 values in a similar range as that of TM." (PMID 32085796, 2020). "Melanoma A375 cells were incubated with different concentrations of Polyphyllin I (0, 1.5, 3.0, and 6.0 mg/L) and PI3K/Akt/mTOR signaling pathway activator IGF-1(20 mg/L)." (PMID 32733943, 2020). "The highest reductions in the activity of metalloproteinases and the invasiveness of melanoma cells were obtained with the combination of the B-RAF inhibitor—PLX-4032 and mTOR inhibitor—everolimus." (PMID 31586300, 2020). "Melanoma cells treated with the PAK inhibitor PF-3758309 displayed increased activation of JNK, β-catenin, and the mTOR signaling pathway and shRNA-mediated gene silencing JNK and β-catenin further decreased melanoma cell viability." (PMID 32252279, 2020). "Together with downstream target protein mTOR, the activated AKT1 induces highly metastatic melanomas involving lung (67%) and brain (17%) in BRAFV600E/Cdkn2aNull mice." (PMID 32962182, 2020). "Importantly, TM also suppressed S6 phosphorylation in non-BRAF mutated melanoma cell lines indicating a broader therapeutic potential of TM in patients without the BRAF mutation but where the PI3K/Akt/mTOR pathway is activated such as in patients harboring NRAS mutations." (PMID 32085796, 2020). "In the present study, we have also shown the involvement of the PI3K/AKT/mTOR signaling pathway in the mechanism behind the ability of IQ to inhibit the proliferation and survival of SK-MEL-2 melanoma cells." (PMID 33260329, 2020). "In conclusion, Polyphyllin I treatment enhanced melanoma cell autophagy and apoptosis, as well as blocked melanoma cell cycle via suppressing PI3K/Akt/mTOR signal pathway." (PMID 32733943, 2020). "In agreement with findings of the present study, other antifungal compounds, namely itraconazole, show potent anti-melanoma action in vivo and in vitro on A-375 and SKMEL-28 cells, down-regulating different pathways including PI3K/mTOR." (PMID 30934896, 2019). "The efficacy of c-Met, mTOR, and AKT inhibitor combinations on resistant melanoma cells was tested in vitro, and a combination of all three inhibitors was found to be very effective." (PMID 31126298, 2019). "The effect of BV and melittin on the PI3K/AKT/mTOR and MAPK activation was therefore investigated in melanoma cells." (PMID 30866426, 2019). "β-Thujaplicin has shown to suppress the phosphorylation of mTOR and Akt and to increase the LC3-II, thereby inhibiting the melanogenesis in B16F10 mouse melanoma cells." (PMID 30874538, 2019). "The oncogenic PI3K/AKT/mTOR and MAPK signaling pathways regulate cell survival, proliferation, migration and invasion, which are key features of malignant melanoma progression." (PMID 30866426, 2019).
melanoma (continued). "Endosulfan, as an organochlorine pesticide, induces autophagy via the AMPK/mTOR signaling pathway triggered by oxidative stress, while Panduratin A, a plant-derived active compound, induces protective autophagy in melanoma via the AMPK and mTOR pathway." (PMID 31001120, 2019). "Treatment with MG132 abolished the degradation of PI3K, AKT, mTOR and ERK proteins by melittin, indicating that melittin induces the proteolysis of these signaling effectors in melanoma cells." (PMID 30866426, 2019). "Curcumin induces apoptosis and autophagy through the inhibition of phosphoinositide 3-kinase (PI3K)/Akt/mTOR pathway in human NSCLC A549 cells, while it induces autophagy by reducing Akt phosphorylation and mTOR in human melanoma A375 and C8161 cells." (PMID 31719837, 2019). "TRIM44, regulated by miR-26b-5p, promotes melanoma progression by stabilizing TLR4, which then activates the AKT/mTOR pathway." (PMID 30922374, 2019). "Of a particular significance, the finding that Ole was able to promote the death effect of Everolimus, a mTOR inhibitor, in Vemurafenib-resistant BRAF melanoma cells, points to a possibility for its use in treating resistant melanoma cells." (PMID 31766676, 2019). "Our results showed that bornyl cis-4-hydroxycinnamate inhibited human melanoma cell metastasis through the MAPKs, FAK/PI3K/Akt/mTOR and GRB2 signaling pathways." (PMID 30042328, 2018). "In parallel experiments, Ole was also able to potentiate an mTOR inhibitor, such as RAD001, which is also in PLX4032-resistant melanoma cells." (PMID 30544808, 2018). "We focused our investigations on the Hippo, AKT, mTOR and MAPK signalling pathways that have been described to mediate proliferation in melanoma cells." (PMID 30068931, 2018). "Potentially relevant proteins include MEK1/2 (8% of melanomas), involved in the MAPK-pathway, and mTOR (10.4% of primary melanomas) or PDK1, involved in the PI3K-Akt-mTOR pathway." (PMID 30460579, 2018). "A recent phase I trial in patients with advanced solid tumors and melanoma shows that HCQ is safe and tolerable and has some antitumor activity when used in combination with temsirolimus-mediated mTOR inhibition." (PMID 29165716, 2018). "In melanoma cells, PD-1 increased phosphorylation of ribosomal protein S6 (RPS6) as an effector of mammalian target of rapamycin (mTOR) signaling." (PMID 30105035, 2018). "In melanoma, the B-raf, β-catenin and PTEN-PI3K/mTOR oncogenic pathways have been identified as direct repressors of tumor-infiltration by T cells." (PMID 30192802, 2018). "We additionally found other routes of GH induced signaling downstream of JAK2 and SRC, including GH-induced increases in phosphorylation states of STAT5, STAT1, STAT3 as well as of AKT, mTOR, and ERK1/2 in all four human melanoma cell lines." (PMID 28223541, 2017). "The expression of four selected genes (MTOR, ABCC1, PLK2 and HDAC4) was validated in nine melanoma cell lines by qPCR." (PMID 28417283, 2017). "Our data suggest that itraconazole inhibits melanoma growth through an interacting regulatory network that includes Hh, Wnt, and PI3K/mTOR signaling pathways." (PMID 28212537, 2017). "They demonstrated expression of HDAC4, MTOR, PLK2, and ABCC1 to be affected in all melanoma cell lines tested." (PMID 28417283, 2017). "Interestingly, a recent study demonstrated that inhibition of autophagy may overcome BRAFi-induced resistance, and a combinatorial inhibition of mTOR and autophagy in a clinical phase I trial in patients with advanced melanoma patients has shown improvement of anti-tumor activity." (PMID 29050198, 2017). "As expected, all the BRAF wt melanoma cell cultures were strongly resistant to PLX4720, but some of them also showed strong resistance to the MEK1/2 or to the PI3K/mTOR inhibitors." (PMID 26678033, 2016).
melanoma (continued). "Recently published studies showed that mutant NRAS melanoma and neuroblastoma cells are highly sensitive to the combination of MEK and combined PI3K/mTOR inhibitors which are in preclinical or early clinical development." (PMID 26821351, 2016). "In conclusion, we demonstrate that upon influence from fibroblasts, melanoma cells undergo a phenotype switch to the mesenchymal state, which can support PI3K/mTOR signaling." (PMID 26918352, 2016). "Materials and methods: Melanoma cell lines and clinical specimens were utilized to study the significance and functional consequences of the PI3K/AKT/mTOR pathway." (PMID 27461275, 2016). "BRAF also cooperates with the PI3K/AKT/mTOR (PI3K) signaling pathway, enhancing melanoma cell invasion and metastasis." (PMID 26517521, 2016). "Autophagy modulation by combined treatment with an mTOR inhibitor (Rapa) and a lysosome inhibitor (HCQ) was shown to be effective in models of breast cancer, melanoma, and glioma." (PMID 25944689, 2015). "Inhibition of PI3K alone with ZSTK474 or PI3K and mTOR with BEZ235 was effective at inhibiting cell proliferation and AKT signaling in all BRAF-mutant melanoma cell lines." (PMID 26137449, 2015). "Phosphorylation of the AMPK/mTOR/p70S6K/rpS6 protein axis was also significantly lower in memory than in naïve CD4+ T cells, with reduced proliferation in the presence of melanoma cells." (PMID 26329660, 2015). "Similar results were observed in B-Raf wild-type melanoma cells as well as in vivo, where treatment of canine AS tumorgrafts with MEK and mTOR inhibitors was more effective than monotherapy." (PMID 25955301, 2015). "Blocking targets in the PI3K/AKT/mTOR pathway by different drugs can reverse resistance to inhibitors of MAPK signaling cascade components, as shown by other authors in melanoma." (PMID 25504439, 2015). "Similar results were observed in B-Raf wild-type melanoma and in vivo, where treatment of canine AS (cAS) tumorgrafts with MEK and mTOR inhibitors is more effective than monotherapy." (PMID 25955301, 2015). "As expected, the treatment with GDC-0980, the dual PI3K/mTOR inhibitor, led to stable inhibition of AKT phosphorylation in both High-RICTOR and Low-RICTOR melanoma cells." (PMID 26356562, 2015). "In melanoma, constitutive activation of the BRAF/MEK/ERK (MAPK) and PI3K/AKT/mTOR (PI3K) signaling pathways plays a pivotal role in cell proliferation, survival and tumorigenesis." (PMID 26299806, 2015). "The PI3K/AKT/mTOR (PI3K) signaling pathway, in addition to MAPK, also plays a vital role in the growth, proliferation and survival of melanoma cells." (PMID 26299806, 2015). "We demonstrate that NexrutineR selectively induces ROS in melanoma cells, resulting in oxidative stress and cell growth inhibition, mediated through PI3K/AKT/mTOR pathway." (PMID 25749517, 2015). "In resistant melanoma cell lines, vemurafenib (BRAF inhibitor) or selumetinib (MEK inhibitor) either fail to suppress P-ERK or resistance emerges through the activity of mammalian target of rapamycin (mTOR), despite P-ERK suppression and BIM induction." (PMID 26639561, 2015). "Treatment with nanomolar levels of mTOR inhibitor, however, rendered these cells as sensitive to MEK inhibition as melanoma with mutant BRAF." (PMID 25955301, 2015). "Our results identify a specific molecular profile of melanomas intrinsically resistant to BRAFi and suggest the PI3K/mTOR pathway as a potential therapeutic target for these tumors." (PMID 25742786, 2015). "In melanoma cell lines, acquired BRAF inhibitor resistance is overcome by simultaneous MEK and PI3K/mTOR inhibition." (PMID 24970815, 2014). "Recent studies have shown that a dual inhibition of MAPK and PI3K/AKT/mTOR pathways leads to a reduction of cell viability in vitro and a decrease in tumor size in xenograft models of NRAS mutant melanoma." (PMID 25277205, 2014).
melanoma (continued). "Oncogenic mutations of the NRAS gene in codons 12, 13 and 61 lead to increased downstream signaling through the well-known NRAS mutant melanoma signaling cascades MAPK and PI3K/AKT/mTOR." (PMID 25277205, 2014). "In conclusion, our data suggest that inhibition of the PI3K/AKT/mTOR signaling pathway by melatonin combined with thapsigargin or tunicamycin efficiently attenuates growth and proliferation of B16F10 melanoma cells." (PMID 24647338, 2014). "Temsirolimus, an mTOR inhibitor (also known as CCI-779), is an analog of Sirolimus (rapamycin) that has demonstrated immunosuppressive activity against melanoma in preclinical models and revealed benefits in patients with breast and renal carcinoma." (PMID 23515890, 2013). "Preclinical studies performed in human melanoma cell lines have highlighted that co-targeting of the Raf/MEK/ERK and PI3K/PTEN/Akt/mTOR pathways with Raf and Akt/mTOR inhibitors resulted in synergistic inhibition." (PMID 23085539, 2012). "The advent of highly specific inhibitors for oncogenic BRAF with robust activity in BRAFV600E mutant melanoma and the clinical development of specific inhibitors of PI3K, AKT and mTOR, provide the tools to translate these concepts into the clinic." (PMID 22194965, 2011). "Altogether, these results indicate that MTA treatment is effective blocking melanoma in vivo tumor growth interfering with the activation of PI3K and mTOR pathways." (PMID 20529342, 2010). "We examined the serum-dependent proliferation of multiple human melanoma cell lines and the effects of inhibition of B-Raf by BAY43-9006 and of mTOR by rapamycin." (PMID 16255777, 2005). "Additionally, SM can be transformed into sphingosylphosphorylcholine (SPC), a bioactive lipid shown to drive melanoma progression by activating key signaling pathways, including ERK, MITF, and Akt/mTOR." (PMID 41596686, 2026). "This study underlines the aberrant activation of the phosphoinositide 3-kinase-protein kinase B - mammalian target of rapamycin (PI3K-Akt-mTOR) and inactivation of the Hippo-YAP pathway, acting as a tumor suppressor in benign-to-malignant transition in melanomas." (PMID 41197182, 2025). "The exogenous H2S donor, NaHS, amplifies the apoptotic process in melanoma A375 and SK-MEL-282 cells, demonstrating the antitumor effect of H2S treatment at high concentrations (via suppression of the PI3K/AKT/mTOR, NF-KB, AKT, ERK1/2, MAPK/ERK, PI3K/Akt pathways, FLIP, XIAP, Bcl-2, PHLDA genes)." (PMID 41373571, 2025). "This article explores the interplay between CSCs and the paracrine renin–angiotensin system in the melanoma TME, and their interaction with the dysregulated Ras/RAF/MAPK/ERK and PI3K/AKT/mTOR signaling pathways, highlighting their implications on current therapeutic approaches." (PMID 39941158, 2025). "The paracrine renin–angiotensin system within the melanoma TME may play an important role in maintaining melanoma CSCs through its interaction with the Ras/RAF/MAPK/ERK and PI3K/AKT/mTOR pathways." (PMID 39941158, 2025). "The mechanistic target of rapamycin (mTOR) pathway serves as a central link between autophagy and NET regulation: activation of autophagy by rapamycin enhances NET production, whereas mTOR activation, such as that observed in melanoma, suppresses it." (PMID 40442839, 2025). "The expression of FAK/PI3K/Akt/mTOR signaling-related proteins, including Akt, p-Akt, PI3K, p-PI3K, mTOR, p-mTOR, and FAK, was reduced in cis-4-hydroxycinnamate treated melanoma cells, which inhibited the metastasis of human melanoma cells through the FAK/PI3K/Akt/mTOR signaling pathway." (PMID 40932870, 2025). "In this article, we explore the mechanisms of resistance to targeted inhibitors, focusing on the interaction between the paracrine renin–angiotensin system within the melanoma TME and the Ras/RAF/MAPK/ERK and PI3K/AKT/mTOR pathways, as well as the role of CSCs regulated by these pathways." (PMID 39941158, 2025).